ANGPTL4 (angiopoietin like 4)
Diseases named in the same sentence as ANGPTL4 in open-access papers (continued):
Sharing a sentence is not in itself a finding about the gene and the disease.
Obesity (continued). "Taken together, these observations give rise to the hypothesis that ANGPTL4 might have a mechanistic function in the development of obesity-related insulin resistance and hyperglycemia." (PMID 34440242, 2021). "Elevated ANGPTL4 and ANGPTL8 levels are also associated with obesity." (PMID 34293055, 2021). "The ANGPTL4 also affected glucose homeostasis and metabolic function in obesity-induced mice." (PMID 33498410, 2021). "However, the research on the regulation of ANGPTL4 expression by gut microbiota in obesity is limited." (PMID 34095196, 2021). "It has been reported that the ANGPTL4 gene is related to obesity and weight management." (PMID 33593372, 2021). "The depletion of ANGPTL4 inhibits obesity-induced angiogenesis and tumor growth." (PMID 34685578, 2021). "Although various studies have tried to find if ANGPTL-4 would be involved in obesity and the associated comorbidities, there is a lack of consensus in this issue." (PMID 31207920, 2019). "Only one study focused on the pediatric age group has shown that circulating ANGPTL-4 levels are significantly lower in children and adolescents with obesity and positively correlated with peroxisome proliferator-activated receptor expression in peripheral blood mononuclear cells." (PMID 31207920, 2019). "All recent data in adults indicate that ANGPTL-4 might have a strong role in metabolism control and might be altered in obesity." (PMID 31207920, 2019). "In both girls and boys with obesity, ANGPTL-4 levels were significantly decreased." (PMID 31207920, 2019). "In this context, the relation between ANGPTL-4 and FFA levels might indicate the possible effect of ANGPTL-4 on obesity." (PMID 31207920, 2019). "Given that ANGPTL-4 is influenced by obesity in pediatric age, we hypothesized that its levels in plasma could be influenced by changes in BMI." (PMID 31207920, 2019). "Since ANGPTL4 expression reduces in obesity, use of probiotics for ANGPTL4 upregulation may be the main target of HFD-induced obesity prevention or treatment." (PMID 31632356, 2019). "Accordingly, in the present paper we investigated the influence of ANGPTL4 on diet-induced obesity and metabolic dysfunction by feeding WT and Angptl4−/− mice a diet rich in unsaturated fatty acids, followed by detailed investigation of the metabolic phenotype." (PMID 29502266, 2018). "Indeed, higher ANGPTL4 concentrations were found as early as 15 weeks of pregnancy in those pregnant women with overweight and obesity that had the highest GWG compared with those with low or appropriate GWG." (PMID 30127377, 2018). "Considering the involvement of ANGPTL4 in fat uptake and storage, and its potential role in glucose metabolism, it is of interest to investigate the role of ANGPTL4 in metabolic dysfunction and insulin sensitivity during obesity." (PMID 29502266, 2018). "Our study shows for the first time that plasma ANGPTL4 concentrations measured in early pregnancy may serve as such a marker in pregnant women with overweight and obesity." (PMID 30127377, 2018). "Considering all these points previously discussed, it would be legitimate to hypothesize that ANGPTL4 transcription regulation by PPARs constitutes a gateway between obesity, insulin sensitivity, and cancer." (PMID 28182091, 2017). "Furthermore, factors secreted by adipose tissue from HFD-induced obese mice and the fat tissue of female patients with obesity led to the upregulation of genes involved in inflammation and lipid metabolism, such as PPARα, IL-1β and ANGPTL4 in triple-negative breast cancer cells." (PMID 36670988, 2023). "Therefore, the ANGPTL4 expression might be one of the key regulators for obesity induced by the dysfunction of gut microbiota." (PMID 34095196, 2021). "In addition, sodium valproate could increase the expression of adipokines in the brain and pituitary (cephalokines), which regulates resistin and angiopoietin-like protein 4 (ANGPTL4) that might have a role in obesity and insulin resistance." (PMID 32952581, 2020).
Obesity (continued). "Therefore, the purpose of this study was to determine, in a population of pregnant women with overweight and obesity, the relationships between their degree of weight gain at the three trimesters of pregnancy with plasma concentration of ANGPTL4 and different lipid variables." (PMID 30127377, 2018). "Finally, the upregulation of ANGPTL4, found consistently in the adipose tissue of morbidly obese women and men, and of Lepob/ob mice, supports the notion that this adipokine plays a crucial role in lipid and glucose metabolism in obesity." (PMID 21182758, 2010). "Hence, our results indicate that ANGPTL4 may be relevant to human obesity and, together with previous findings, point to this protein as a potential therapeutic target for obesity and obesity-related complications." (PMID 21182758, 2010). "Obesity triggers a phenotypic change in gastric SMCs, driven by the activation of the PPARD/PDK4/ANGPTL4 pathway." (PMID 40652248, 2025). "This study reveals a novel mechanistic link between obesity and gastric smooth muscle dysfunction, implicating the activation of the PPARD/PDK4/ANGPTL4 pathway." (PMID 40652248, 2025). "Our analysis of clinical datasets reveals that ANGPTL4 and KLF4 expression are significantly elevated in TNBC patients, particularly those with obesity, and correlates with poor prognosis." (PMID 40616161, 2025). "Elevated serum ANGPTL4 levels were correlated with several metabolic diseases, such as type 2 diabetes mellitus (T2DM), obesity, and CVD." (PMID 38574398, 2024). "The detrimental effect of obesity on CAD appears to be primarily mediated by MAP1LC3A, ANGPTL4, RPS6KA1, PCSK9, ITPKA, and AGER." (PMID 38049831, 2023). "Circulating levels of AHSG, ANGPTL4 and LECT2 were previously demonstrated to correlate with obesity, BMI or waist circumference in humans." (PMID 35409319, 2022). "Multiple members of this protein family are closely related to obesity and obesity-related metabolic diseases: ﻿ANGPTL3, ANGPTL4, and ANGPTL6 can directly regulate lipid, glucose, and energy metabolism without exerting angiogenic effects." (PMID 32299395, 2020). "Obesity negatively impacted the sWAT-MSC secretome, since its anti-oxidant (GCL, Prdx5, Prdx6) and tissue development (Ang, Angptl4, Fstl3, Pgf) activities were lost, while factors promoting osteoporosis and negative vessel remodeling were acquired." (PMID 32727501, 2020). "The c-terminal fibrinogen-like domain of angiopoietin-like 4 (FLD of Angptl4) induces cAMP-PKA-dependent lipolysis in white adipocytes and reduces diet-induced obesity." (PMID 33227979, 2020). "Our findings provide insights into the understanding of ANGPTL4 and LPL pathways in human adipose tissue and add knowledge on ANGPTL4 involvement in glucose regulation in obesity." (PMID 33003532, 2020). "This study was designed to explore VAT ANGPTL4 and LPL expression levels in human obesity in relation to adipose tissue inflammation, impairment in glucose metabolism, and clinical outcomes." (PMID 33003532, 2020). "Obesity negatively impacted sWAT-MSC secretome: the anti-oxidant (GCL, Prdx5, Prdx6) and tissue development (Ang, Angptl4, Fstl3, Pgf) activities were lost, while factors promoting osteoporosis and negative vessel remodeling were acquired." (PMID 32727501, 2020). "However, in children, the precise role of ANGPTL-4 in obesity remains unknown." (PMID 31207920, 2019). "As both ANGPTL3 and ANGPTL4 are important in lipid metabolism through their interaction with lipoprotein lipase, our data suggest a role for ANGPTL5 in TGL metabolism in obesity." (PMID 31396158, 2019). "However, the relevance of ANGPTL4 during obesity and atherosclerosis could not be explored previously because global ANGPTL4-deficient mice fed an HFD or WD develop a severe and lethal phenotype, characterized by massive intestinal inflammation and fibrosis." (PMID 29563332, 2018).
Obesity (continued). "The purpose of this study is to determine whether the ANGPTL4 E40K and T266M polymorphisms are associated with triglyceride levels in well characterized patients with T2D, and with CVD risk factors, such as metabolic syndrome and obesity in type 2 diabetic Tunisian population." (PMID 27004807, 2016). "Furthermore, a significant positive correlation was observed between ANGPTL4 and PDK4 mRNA levels in patients with obesity, suggesting a link between their expression." (PMID 40652248, 2025). "Angptl4-knockout mice fed a HFD were reported to develop a severe inflammatory phenotype, which led to their premature death and precluded further studies on the role of Angptl4 in diet-induced obesity." (PMID 36074318, 2022). "As 24-h fasting in humans has been shown to increase mRNA and protein ANGPTL4 in mammary WAT, fasting may accelerate obesity-induced tumor angiogenesis." (PMID 35186923, 2022). "Although the potential therapeutic relevance of modulating the expression/activity of AHSG, ANGPTL4, LECT2 and FGF21 for treating obesity, IR and liver metabolic disorders is still unclear, targeting these hepatokines appears to be a promising strategy in addition to other currently used therapies." (PMID 35409319, 2022). "The present study, which monitored diabetes patients, revealed that a significant correlation among obesity, glucose metabolism markers, and ANGPTL4 is lacking." (PMID 34293055, 2021). "Therefore, this study aimed to investigate ANGPTL4 and LPL expression in visceral AT (VAT) in relation to (i) local inflammation and dysfunction and (ii) clinical alterations, in human obesity." (PMID 33003532, 2020). "Accordingly, the present work shows a decrease in ANGPTL-4 levels in children and adolescents with obesity independent of the gender and pubertal stage." (PMID 31207920, 2019). "When the correlation study was performed independent of the obesity diagnosis, it was found that all correlations between ANGPTL-4 and anthropometric and biochemical characteristics were absent in individuals with normal weight." (PMID 31207920, 2019). "In addition, the main biochemical parameters altered in obesity (FFA, cholesterol, vitamin D, etc.)are correlated with ANGPTL-4 levels." (PMID 31207920, 2019). "In addition to the changes in the plasma concentration of ANGPTL4, we found that GWG in pregnant women with obesity was related negatively to LA (18:2, n-6) and positively to saturated fatty acids, especially SA (18:0), concentrations in plasma." (PMID 30127377, 2018). "ANGPTL4 mRNA expression in SAT was affected neither by the presence of obesity/T2DM nor by weight-reducing interventions." (PMID 29695708, 2018). "To further study the impact of the gut microbiota on the effect of Angptl4 ablation on glucose tolerance, we repeated the diet-induced obesity study in WT and Angptl4−/− mice with or without antibiotics in their drinking water (study 2)." (PMID 29502266, 2018). "In addition, although both plasma ANGPTL4 and PLTP activity were expectedly correlated with obesity and NEFA, ANGPTL4 was inversely correlated with total cholesterol and LDL cholesterol, whereas PLTP activity was significantly correlated with triglycerides." (PMID 29587751, 2018). "Importantly, we found a significant increase in PDK4 expression in gastric smooth muscle fibers from patients with obesity compared to controls, while ANGPTL4 levels showed a slight but non-significant increase." (PMID 40652248, 2025). "In addition, a negative correlation between ANGPTL-4 and total cholesterol was observed in individuals with obesity." (PMID 31207920, 2019). "However, different from adults, we show that the relation between ANGPTL-4 and obesity is independent of the age in the pediatric population." (PMID 31207920, 2019).
Obesity (continued). "Finally, we analyzed the data as a function of pubertal stage separately in girls and boys and found that the decrease in circulating ANGPTL-4 in individuals with obesity was independent of the gender and the pubertal stage." (PMID 31207920, 2019). "In contrast, other studies have not found a relation between ANGPTL-4 and obesity." (PMID 31207920, 2019). "Therefore, we conclude that small intestinal Angptl4 is probably not a main contributor to development of obesity in our mouse model." (PMID 18457598, 2008). "Also genes with a pronounced differential gene expression, of which function is not completely elucidated yet (e.g. Angptl4, H2-Q10, Oit1, Smpdl3a/b) are potential interesting signaling molecules that might contribute to development of obesity and/or insulin resistance." (PMID 18457598, 2008). "Although the regulatory mechanism for this expression is unknown, ANGPTL4 and IL-1β may contribute to the development of atherosclerosis via the induction of local inflammation around EAT in individuals without obesity." (PMID 35566578, 2022). "Unlike ANGPTL4, the relationship of ANGPTL3 and obesity and T2DM is less clear." (PMID 29695708, 2018).
diabetes (64 papers, 2010 to 2025). "Multivariable regression further showed that both prediabetes and diabetes were independently associated with higher ANGPTL4 levels." (PMID 41226996, 2025). "Severe systemic metabolic complications such as gut inflammation and ascites have limited investigators’ ability to analyze the beneficial functions of Angptl4 deficiency in diabetes." (PMID 39630889, 2024). "Decreased mtDNA release as well as decreased STING activation down-regulated pro-inflammatory cytokine expression in diabetes, suggesting that Angptl4 deficiency can restore mitochondrial homeostasis." (PMID 39630889, 2024). "Genetic deficiency of Angptl4 improves glucose homeostasis and diabetes and hepatocyte-deficient mutant mice demonstrate improved hepatocyte FAO and associated improvements in obesity, diabetes, and atherosclerosis." (PMID 39630889, 2024). "ANGPTL4 is a released glycoprotein that regulates lipid metabolism and insulin sensitivity; thus, alterations in ANGPTL4 expression affect the risk of developing atherosclerosis and type 2 diabetes mellitus." (PMID 37509544, 2023). "Multiple regression analysis was performed on relationships to ANGPTL4 expression of combinations of possible determinants of age, gender, and clinical risk factors (diabetes mellitus and hyperlipidemia)." (PMID 35566578, 2022). "Human genetics studies show that inactivating mutations in the ANGPTL4 gene (E40K) improve glucose and lipid homeostasis and reduce the risk of coronary artery disease and diabetes." (PMID 35860030, 2022). "The human genetics studies showed that genetic inactivation of ANGPTL4 improves glucose and lipid homeostasis and is associated with reduced risk of coronary artery disease and diabetes." (PMID 34616362, 2021). "Multiple studies have revealed that metabolic syndrome is a risk factor for diabetes mellitus, hypertension, pro-inflammatory state, central adiposity, dyslipidemia and high concentrations of ANGPTL4." (PMID 31164103, 2019). "Gagnon and colleagues (2024) demonstrated that the inhibition of ANGPTL4 reduced the risk of CAD and diabetes, demonstrating that ANGPTL4 inhibition may represent an effective target for the prevention or treatment of cardiometabolic diseases." (PMID 39728292, 2024). "Angiopoietin-like protein 4 (ANGPTL4), encoding a glycosylated secreted protein, has been reported to be closely related to many kinds of diseases, including diabetes, tumor, and some musculoskeletal pathologies, such as rheumatoid arthritis, osteoarthritis, and osteoporosis." (PMID 34876931, 2021). "In this study we show an opposite association pattern of serum ANGPTL3 and ANGPTL4 with body weight, diabetes status, and parameters of glucose control across a wide range of BMI as well as their different reactions to short- and long-term weight-modifying interventions." (PMID 29695708, 2018). "First, the level of protection from coronary disease and diabetes associated with the ANGPTL4 p.Glu40Lys variant is the same as that of LPL alleles for a given genetic difference in triglyceride levels and is consistent across the population distribution of LDL-C–lowering alleles." (PMID 30326043, 2018). "The ANGPTL4 p.Glu40Lys variant was associated with protection from coronary disease and diabetes, with effect estimates nearly identical to the ones of triglyceride-lowering alleles in LPL for a given genetic difference in triglyceride levels (eFigure 2 in the Supplement)." (PMID 30326043, 2018). "However, the complex causal link between serum ANGPTL4 concentrations, hepatic steatosis and type 2 diabetes mellitus remain unclear." (PMID 41226996, 2025). "However, on the basis of previous and current data, we suspect that diabetes may cause renal secretion of the hyposialylated form of Angptl4 protein." (PMID 39630889, 2024).